SIRT1 (sirtuin 1)
Diseases named in the same sentence as SIRT1 in open-access papers (continued):
Sharing a sentence is not in itself a finding about the gene and the disease.
triple-negative breast carcinoma (20 papers, 2015 to 2025). An invasive breast carcinoma which is negative for expression of estrogen receptor (ER), progesterone receptor (PR), and human epidermal growth factor receptor 2 (HER2). "Moreover, SIRT1 expression was associated with tumor progression and poor prognosis in triple-negative breast cancer." (PMID 35252011, 2022). "Montelukast was shown to suppress EMT and angiogenesis in triple-negative breast cancer (TNBC) through inhibition of the SIRT1/AKT signaling axis, reducing SIRT1 and vimentin expression while upregulating E-cadherin." (PMID 41471349, 2025). "SIRT1 is proposed as a prognostic indicator as well as a novel therapeutic candidate in triple-negative breast cancer (TNBC)." (PMID 35203617, 2022). "Analysis of the mRNA expression of the FoxO family and SIRT1 in TCGA (The Cancer Genome Atlas) revealed that all genes were downregulation in tumors compared to normal tissues in TNBC (triple-negative breast cancer) (p < 0.05 for FoxO1, FoxO4)." (PMID 36142156, 2022). "A SIRT1 activator YK-3-237 was reported to inhibit the proliferation of triple-negative breast cancer cells." (PMID 29991742, 2018). "By suppressing the activities of Sirtuin 1 (SIRT1) and DNMTs, resveratrol and pterostilbene can synergistically inhibit cell viability, induce apoptosis, and arrest the cell cycle in triple-negative breast cancer cells, inhibiting telomerase activity and histone H2AX expression." (PMID 37111085, 2023). "Moreover, our results are the first to demonstrate that SIRT-1 and HDACs regulate DVL-1 acetylation levels and pharmacological inhibition of these lysine deacetylases results in altered acetylation levels of DVL-1 in two triple-negative breast cancer cell lines." (PMID 31700102, 2019).
lung adenocarcinoma (19 papers, 2014 to 2025). A carcinoma that arises from the lung and is characterized by the presence of malignant glandular epithelial cells. "The results of the cell proliferation and apoptosis assays confirmed that the ferroptosis program promoted by SIRT1–AMPK–ACC signaling mediated by the overload of NAM was associated with lung adenocarcinoma cell proliferation and apoptosis in vitro." (PMID 37173894, 2023). "For example, SIRT1 transgenic or overexpression mice are less susceptible to cancers, i.e. liver carcinogenesis, lung adenocarcinomas and intestinal cancers." (PMID 31598701, 2019). "In order to evaluate the role of Sirt1 in lung adenocarcinoma, Sirt1 expression was investigated in association with any of the clinicopathological variables in the 125 enrolled cases of primary lung adenocarcinoma." (PMID 24959282, 2014). "A significant association was found between HIF1 expression levels and a Sirt1-positive signal in patients with primary lung adenocarcinoma (P=0.05), and there was a negative regulation between them." (PMID 24959282, 2014). "The findings presented in the current study show for the first time that Sirt1 overexpression in lung adenocarcinoma tissue specimens is associated with HIF1 expression, Ki67 index, TNM stage, pulmonary vein invasion and lymphatic duct invasion." (PMID 24959282, 2014). "Sirt1 may thus be associated with a poor prognosis for lung adenocarcinoma." (PMID 24959282, 2014). "Here, NAM, one of its metabolites, intracellularly accumulated in massive amounts in lung adenocarcinoma cells and significantly inhibited SIRT1 activity." (PMID 37173894, 2023). "CircRNA has-circ-0001946 promotes cell growth in lung adenocarcinoma by regulating miR-135a-5p/SIRT1 axis and activating Wnt/β-catenin signaling pathway." (PMID 38033864, 2023). "A recent study has shown that SIRT1 can selectively eliminate EGFR TKI-resistant cancer stem cells by regulating mitochondrial oxidative phosphorylation in lung adenocarcinoma." (PMID 37242510, 2023). "The expression status of Sirt1 was determined in 125 lung adenocarcinoma and adjacent normal lung tissues by IHC, with the use of rabbit anti-human monoclonal antibody." (PMID 24959282, 2014). "In total, 125 surgically resected lung adenocarcinoma specimens were examined to determine the Sirt1 status in cancer cells and tissue clinically by IHC staining." (PMID 24959282, 2014). "Immunohistochemical staining was performed to investigate Sirt1 expression in cancer cells in 125 consecutive resected cases of primary lung adenocarcinoma." (PMID 24959282, 2014). "It is indicated that overexpression of Sirt1 may be correlated with a poor prognosis for lung adenocarcinoma again." (PMID 24959282, 2014). "In addition, another study indicated that circ_0001946 could promote cell growth in lung adenocarcinoma by regulating miR-135a-5p/SIRT1 axis and activating Wnt/β-catenin signaling pathway." (PMID 32508871, 2020). "Overall, high-dose NMN treatment promoted ferroptosis to suppress lung adenocarcinoma growth through an excessive accumulation of NAM and the NAM-mediated SIRT1–AMPK–ACC pathway." (PMID 37173894, 2023). "However, Sirt1 expression in primary lung adenocarcinoma remains unknown." (PMID 24959282, 2014). "Due to silybin being a potent inhibitor of lung adenocarcinoma cell growth that interferes with SIRT1 signaling, combinatorial treatment with CAM/silybin may be used for therapeutic intervention in lung adenocarcinoma therapy in the future." (PMID 35900723, 2022).
malnutrition (19 papers, 2018 to 2025). Inadequate nutrition resulting from poor diet, malabsorption, or abnormal nutrient distribution. "In contrast, SIRT-1 and melatonin showed limited clinical significance due to their insufficient sensitivity in assessing malnutrition risk." (PMID 40005054, 2025). "It should be emphasized that SIRT1 is involved in reacting to metabolic imbalances caused by caloric restriction and malnutrition." (PMID 39062007, 2024). "Our results are consistent with a clinical study reporting that increased malnutrition risk was associated with decreased SIRT1 expression." (PMID 36481684, 2022). "Multiple factors regulate AMPK/SIRT1, including inflammatory factors, nutritional deficiency, and oxidative damage, and are associated with IVDD." (PMID 35669720, 2022). "A reduction in SIRT-1 activity may contribute to an increased risk of developing diseases that are associated with malnutrition." (PMID 40005054, 2025). "CCK-8 emerged as a strong predictor of malnutrition risk (AUC = 0.58 in females, AUC = 0.64 in males), whereas SIRT-1 (AUC = 0.57 for both sexes), melatonin (AUC = 0.46 for females, AUC = 0.51 for males), and TAC (AUC = 0.42 for females, AUC = 0.54 for males) exhibited weaker predictive abilities." (PMID 40005054, 2025). "Since malnutrition which referred to deficiencies in energy or nutrient uptake commonly caused growth retardation, we tested expression levels of hepatic Fgf21 and Sirt1, key genes for Igf1 inhibition under malnutrition condition." (PMID 40598150, 2025). "This study explores the relationship between SIRT-1, CCK-8, melatonin, and TAC in the context of malnutrition risk among older adults, addressing an area that has received limited attention." (PMID 40005054, 2025). "The current study offers a more comprehensive understanding of the potential role of SIRT-1 in the regulation of appetite, particularly in the context of the multifaceted mechanisms that lead to malnutrition." (PMID 40005054, 2025). "This study investigates the potential role of biochemical biomarkers such as sirtuin 1 (SIRT-1), melatonin, cholecystokinin-8 (CCK-8), and total antioxidant capacity (TAC) in identifying the risk of malnutrition." (PMID 40005054, 2025). "In assessing the predictive value of SIRT-1, cholecystokinin-8, melatonin, and TAC for the risk of malnutrition, optimal cut-off points were established for both male and female participants." (PMID 40005054, 2025). "In the present study, SIRT-1, melatonin, CCK-8, and TAC were found to have differential diagnostic utility in assessing the risk of malnutrition in elderly individuals." (PMID 40005054, 2025). "Whereas in a fasting state, caloric restriction or malnutrition, SIRT1 intensifies catabolic processes and inhibits anabolic processes to maintain homeostasis." (PMID 38529393, 2024). "During malnutrition, SIRT1 blocks GH signal transduction in hepatocytes to reduce the IGF-1 secretion and prevent hypoglycemia (i.e., it causes transient GH resistance)." (PMID 37895086, 2023). "Our SIRT1 modulation experiments demonstrated that in our malnutrition model, the effects of NAM were dependent on the presence of SIRT1 and that stimulating SIRT1 was sufficient to produce beneficial effects on mitochondrial function." (PMID 36481684, 2022). "Although, we provide evidence for a role of SIRT1 in the altered mitochondrial homeostasis and function in malnutrition, we cannot exclude SIRT1-independent effects." (PMID 36481684, 2022). "In conclusion, this work provides evidence for the role of the TRP-NAD+ pathway in liver metabolic dysfunction in a mouse model of severe malnutrition, potentially mediated through changes in levels of SIRT1." (PMID 36481684, 2022). "Together our results indicate that malnutrition‐induced downregulation of SIRT1 impairs mitochondrial homeostasis and metabolic capacity in skeletal muscle through decreased PGC‐1α and PINK1." (PMID 33650806, 2021).
malnutrition (continued). "The purposes of this study were to 1) investigate the differences in the metabolic capacity of fast and slow muscles under malnourished condition, and 2) examine the changes in oxidative stress and the energy‐sensing of AMPK/SIRT1 in malnutrition." (PMID 33650806, 2021). "The purpose of the present study was to investigate the effects of metabolic capacity in fast and slow muscles via the energy‐sensing of AMPK and SIRT1 in malnutrition." (PMID 33650806, 2021). "An adverse effect of malnutrition on the growth process with blockage of IGF-1 secretion by sirtuin 1 (SIRT1) was described." (PMID 34445772, 2021). "Malnutrition impaired mitochondrial metabolic capacity via downregulating SIRT1 induced by increased oxidative stress in both fast and slow muscles although no atrophy was observed in slow muscle." (PMID 33650806, 2021). "The energy‐sensing in malnutrition was characterized by AMPK‐independent SIRT1 inhibition in both fast and slow muscles." (PMID 33650806, 2021). "In contrast, malnutrition raises SIRT1 levels, prolongs the repression of Kiss1 by SIRT1, and delays puberty." (PMID 33572672, 2021). "During exercise or nutritional deficiency, AMPK activation increases the level of intracellular NAD+, activates Sirt1 and eventually catalyzes the deacetylation of Pgc-1α." (PMID 32835596, 2020). "Conclusively, SIRT1 plays an important role in switching from growth to survival mode in order to adapt to malnutrition by modulating the somatotropic axis at various steps." (PMID 30405528, 2018). "Therefore, future research should investigate the role of SIRT-1 and melatonin in individuals with diagnosed malnutrition." (PMID 40005054, 2025). "It was proven that, SIRT1 play an important role in detection of cellular energy levels and regulation of energy metabolism and increase in response to fasting, caloric restriction and malnutrition." (PMID 38529393, 2024). "The amount of SIRT1 depends on the availability and type of nutrients, because this nutrient-responsive protein is involved in responding to metabolic imbalances that are triggered by fasting, caloric restriction, and malnutrition." (PMID 37895086, 2023). "Thus, it appears that in children with malnutrition, the level of SIRT1 is increased to inhibit peripheral IGF-1 production and maintain homeostasis." (PMID 37895086, 2023). "Activation of SIRT1 might be beneficial for sarcopenic obesity, malnutrition and glucocorticoid-induced atrophy." (PMID 35370668, 2022). "In addition, the energy‐sensing response of both muscles in malnutrition was characterized by AMPK‐independent SIRT1 inhibition induced by increased oxidative stress." (PMID 33650806, 2021). "However, the expression of SIRT1 protein in both muscles was significantly lower in the malnutrition group than that in the control group." (PMID 33650806, 2021). "Conversely, the expression level of SIRT1 decreased in both muscles of the malnutrition group." (PMID 33650806, 2021). "However, the expression of SIRT1 protein decreased despite an increase in AMPK expression in both muscles of the malnutrition group." (PMID 33650806, 2021). "SIRT1 is involved in the production of various hormones and maintenance of homeostasis by regulating the function of histones and transcription factors, to adapt to malnutrition in the endocrine and metabolic systems." (PMID 30405528, 2018). "Thus, malnutrition‐induced downregulation of the SIRT1/PGC‐1α pathway may impair mitochondrial biogenesis in skeletal muscle." (PMID 33650806, 2021). "SIRT1-dependent negative regulation of GH-induced IGF-1 production seems to be an adaptive mechanism under fasting conditions and malnutrition." (PMID 37895086, 2023). "While malnutrition is indeed a secondary manifestation of metabolic and renal dysfunction, nutrient sensing dysregulation (e.g., via AMPK/SIRT1/mTORC1 pathways) constitutes a pivotal mechanism in DKD progression, deeply intertwined with oxidative stress and autophagy impairment." (PMID 40337513, 2025).
malnutrition (continued). "The effects of malnutrition on the energy‐sensing response of AMPK and SIRT1 are also unknown." (PMID 33650806, 2021). "It seems that SIRT1, which regulates the JAK2/STAT pathway, may be involved in peripheral GH resistance and be responsible for the reduced IGF-1 concentration in some conditions (e.g., malnutrition) that require increased glucose production to prevent hypoglycaemia." (PMID 37895086, 2023).
schizophrenia (18 papers, 2014 to 2025). A major psychotic disorder characterized by abnormalities in the perception or expression of reality. "A ceRNA network was built on highly intersected lncRNA-miRNA-mRNA which included one lncRNA, 2miRNAs (miR-26a-5p and miR-22-3p) and 2 mRNA (EZH2 and SIRT1) and concluded that network have the potential as diagnostic molecular signal in early schizophrenia." (PMID 39939309, 2025). "Later, we attempted to identify the association of SIRT1 mRNA and the rs3758391 polymorphism with susceptibility to schizophrenia and associated depressive symptoms." (PMID 32849821, 2020). "The main limitations are obviously the cross-sectional nature of our study, which preclude us to make firm conclusions about the directionality of SIRT1, inflammatory cytokine on MetS caused by SGAs in schizophrenia patients." (PMID 33324265, 2020). "Taken together, we performed a clinical study to examine the association between SIRT1, inflammatory cytokines, and MetS in schizophrenia patients receiving long-term olanzapine or clozapine monotherapy." (PMID 33324265, 2020). "To further figure out which metabolic components were significantly associated with SIRT1 in schizophrenia patients, we performed correlation analysis and found that SIRT1 was inversely or positively associated with DBP, TG, and HDL, but not GLU." (PMID 33324265, 2020). "Subsequently, genetic studies in Eastern Asian populations (mainly Japanese and Chinese Han populations) indicated that the SIRT1 gene is associated with schizophrenia." (PMID 32849821, 2020). "And our previous work also indicated that low plasma SIRT1 levels in schizophrenia patients are associated with depressive symptoms." (PMID 32849821, 2020). "Our preliminary findings provide suggestive evidence that SIRT1 confers susceptibility to depressive symptoms in schizophrenia." (PMID 32849821, 2020). "A promising mechanism underlying the SIRT1 involved in MetS in schizophrenia patients may be associated with the activation of the immune inflammatory system." (PMID 33324265, 2020). "Therefore, at least in Asian populations, SIRT1 variation is likely to contribute to the risk of schizophrenia." (PMID 32849821, 2020). "Therefore, a longitudinal study with larger study samples and with best measure to reduce the confounding effect is required to evaluate causal relations between SIRT1, immune inflammation, and MetS in schizophrenia patients." (PMID 33324265, 2020). "Therefore, we aimed to identify the impact of SIRT1 rs3758391 polymorphism on the genetics and symptoms of schizophrenia in this research." (PMID 32849821, 2020). "However, little is known about the relationship between SIRT1 and SGAs-caused MetS in schizophrenia patients." (PMID 33324265, 2020). "These consistent results indicated that genetic variation resulting from the rs3758391 polymorphism might lead to the dysregulation of SIRT1 mRNA expression and exert a significant influence on the occurrence and development of depressive symptoms in schizophrenia." (PMID 32849821, 2020). "We hypothesized that the reduced SIRT1 plasma levels may be associated with altered inflammatory cytokines in schizophrenia, and the interaction between SIRT1 and cytokines may contribute to the MetS caused by SGAs in schizophrenia patients." (PMID 33324265, 2020). "The SIRT1 gene is another candidate gene in cluster 1, which was associated with schizophrenia in a haplotype-wise analysis and may play an important role in the pathophysiology of schizophrenia in the Japanese population." (PMID 25522158, 2014). "Kaempferol, a polyphenol, has exhibited neuroprotection in rat models of hippocampal damage and memory deficits via the activation of SIRT1 – a neuroprotective gene in schizophrenia." (PMID 38321095, 2024). "In all patients with schizophrenia, our results showed that plasma levels of SIRT1 were negatively correlated with IL-6 (r = −0.345, P = 0.011), IL-10 (r = −0.276, P = 0.043), and TNF-α (r = −0.393, P = 0.003)." (PMID 33324265, 2020).